HMGA2 (high mobility group AT-hook 2)
Diseases named in the same sentence as HMGA2 in open-access papers (continued):
Sharing a sentence is not in itself a finding about the gene and the disease.
breast cancer (continued). "We confirmed that 8 genes—MAPK14, CLOCK, NF2, HMGA2, CXCL12, E2F1, NOTCH1, and CD24—are associated with breast cancer." (PMID 30013305, 2018). "HMGA2 has been identified as an oncoprotein that is frequently upregulated in a variety of cancers, including breast cancer, esophageal squamous carcinoma, colorectal cancer, ovarian tumors." (PMID 30474570, 2018). "PTPRN2, MERTK, TNC and SOX4 were identified to be targets of miR-335, AIB1 and CCND1 were the targets of miR-17-5p, and H-RAS and HMGA2 were verified as targets of let-7 in breast cancer." (PMID 30309377, 2018). "HMGA2 was found upregulated in various cancers, such as lung cancer, breast cancer, and oral squamous cell carcinomas." (PMID 28487599, 2017). "HMGA2 is part of a larger STAT3/LIN28/Let‐7/HMGA2 axis with important oncogenic functions in a subset of GB and breast cancer cells." (PMID 28500786, 2017). "Our data show that SID peptide downregulates Wnt/β-catenin reporter activity and direct Wnt target genes (LEF1, TCF7L2, CD44, PLAU, MT1-MMP, MMP9, HMGA2) involved in breast cancer invasion and metastasis." (PMID 29179446, 2017). "We initially identified 1337 (FClog2 ≤ 0.5, p ≤ 0.05) potential HMGA2-targets by exploration of expression profiling data of the breast cancer cell line MDA-MB-231 with HMGA2 knock-down (GSE4374137)." (PMID 28852061, 2017). "HMGA2 has been also detected in phyllodes breast cancers where it was always overexpressed in border line and malignant neoplasias and rarely in benign cases, suggesting its involvement during benignity to malignancy transition." (PMID 25859543, 2015). "The mechanism through which miR-33b inhibits the stemness, migration and invasion of breast cancer cells is by targeting HMGA2, SALL4 and Twist1." (PMID 25919570, 2015). "Silencing of HMGA2 in the invasive breast cancer cell model MDA-MB-231 affected, in addition to E-cadherin, the expression of invasive genes, such as MMP2 and TNC, and reduced the rate of motility and infiltration of cells through matrigel." (PMID 25492890, 2015). "miR-33b can inhibit the self-renewal of breast cancer cells and their migration and invasion capabilities by targeting HMGA2, SALL4 and Twist1." (PMID 25919570, 2015). "We currently conduct a ChIP-seq analysis of HMGA2 in breast cancer cells to help identify and better understand the regulation of alternative gene targets by HMGA2 during breast cancer cell invasion." (PMID 25492890, 2015). "Collectively, these data indicate that miR-33b can inhibit breast cancer stem-like cell self-renewal by targeting HMGA2, SALL4 and Twist1." (PMID 25919570, 2015). "Although the direct regulatory relationship between let-7a and HMGA2 has been confirmed in lung cancer, breast cancer, and esophageal cancer, little is known about let-7 and HMGA2 in NPC." (PMID 25884389, 2015). "These two genes, MTDH and HMGA2, are known as oncogenes in a variety of human cancers; MTDH protein is over-expressed and promotes metastatic seeding in breast cancer and over-expression of HMGA2 also induces metastasis and invasion of human cancer cells." (PMID 25340791, 2014). "It regulates numerous oncogenes, like RAS, MYC and HMGA2, it was found to be down-modulated in different cancer types and restoration in breast cancer inhibited tumor growth, validating its role as tumor-suppressor." (PMID 24284394, 2013). "Downregulation of let-7 following chemotherapeutic treatment has been shown to increase stemness and tumorigenicity of breast cancer cells through regulation of multiple targets including the let-7 targets c-Myc, Ras, and HMGA2." (PMID 23166734, 2012). "Furthermore, LINC01121 directly interacts with miR-150-5P, leading to the increase of HMGA2 level, which regulates metastasis in breast cancer." (PMID 41488287, 2026). "Similarly, in breast cancer, Let-7a downregulates HMGA2 and c-Myc, contributing to reduced cell proliferation and increased apoptotic activity." (PMID 40063190, 2025).
breast cancer (continued). "In breast cancer, the promoter of HMGA2 is demethylated in TNBC tumors or overexpressed in breast cancer tissues, leading to an increase at the mRNA and protein levels of HMGA2, which in turn plays a crucial role in promoting cell proliferation and conferring stem cell-like features." (PMID 38802807, 2024). "While several studies have assessed different polymorphism of the HMGA2 gene in various cancers, there is no report about breast cancer." (PMID 38802807, 2024). "Moreover, the upregulation of Raf kinase inhibitory protein (RKIP) can induce the upregulation of miRNA-185, which subsequently suppresses HMGA2 expression, resulting in the inhibition of breast cancer cell growth and invasion." (PMID 38802807, 2024). "Furthermore, it has been reported that HMGA2 acts as a functional antagonist of PARP1 inhibitors in breast cancer cell lines." (PMID 38778348, 2024). "The high mobility group A2 (HMGA2) gene is expressed extensively during early embryonic development but is inactivated in adulthood, and it is also reactivated in various benign and malignant tumors, including breast cancer." (PMID 38802807, 2024). "HMGA2 is expressed extensively during early embryonic development, but in adulthood, it is primarily expressed in the liver, kidney, and uterus; however, it is also reactivated in various benign and malignant tumors, including breast cancer." (PMID 38802807, 2024). "There are studies about the association of polymorphisms in HMGA2 with the risk of some cancers, but there is no report about HMGA2 polymorphisms in breast cancer." (PMID 38802807, 2024). "Furthermore, HMGA2 is often found to be highly expressed in various types of tumors and has garnered significant attention in cancer research, including research on breast cancer, lung cancer, pancreatic cancer, etc.." (PMID 39335310, 2024). "HMGA2 is involved in the tumorigenesis and progression of different malignancies, included but not limited to lung cancer, breast cancer, acute myeloid leukemia, ovarian cancer, clear cell renal cell carcinoma, head and neck cancer, hepatocellular carcinoma, pancreatic cancer, and gastric cancer." (PMID 35388973, 2022). "Furthermore, miR-211 inhibits cells migration and invasion ability, and reverse the EMT phenotype by downregulating high mobility group A2 (HMGA2) in breast cancer." (PMID 35912006, 2022). "VGLL3 or HMGA2 knockdown repressed the motility of the mesenchymal breast cancer MDA‐MB‐231 cells." (PMID 35366053, 2022). "Based on the findings, we suggest that the newly developed G4/MTX-siRNA nano-complex may be a promising strategy to increase apoptosis induction through HMGA2 suppression as a therapeutic target in human breast cancer." (PMID 34356120, 2021). "As is the case for NFκB, the activation of STAT3 in breast cancer promotes the transcription of Lin28B by directly binding to the Lin28B promoter, resulting in the repression of let-7 expression and concomitant upregulation of the let-7 target, HMGA2." (PMID 34572067, 2021). "For example, the well-characterized lncRNA HOTAIR could promote proliferation and metastasis of breast cancer through either regulating miR-20a-5p/HMGA2 pathway or enhancing the ER expression and ER occupancy on its downstream target genes." (PMID 34244473, 2021). "Additionally, our previous study showed that HMGA2 silencing using mature specific siRNAs sensitizes breast cancer cells to paclitaxel." (PMID 33668453, 2021). "Here, methotrexate (MTX)- modified polyamidoamine dendrimer generation 4 (G4) (G4/MTX) was generated to deliver specific small interface RNA (siRNA) for suppressing HMGA2 expression and the consequent effects on folate receptor (FR) expressing human breast cancer cell lines (MCF-7, MDA-MB-231)." (PMID 34356120, 2021).
breast cancer (continued). "Besides, HMGA2 protein expression in breast cancer samples from the Cancer Institute’s Clinical Proteomic Tumor Consortium (CPTAC) showed that the HMGA2 protein levels were increased in TNBC samples compared to normal tissues (p < 0,05)." (PMID 34680349, 2021). "In addition, we found HMGA2 knockdown increased CD24+ CD44+ breast cancer in moderate HMGA2 expressed cell line and increased CD24+ CD44- in HMGA2 overexpressed cell lines." (PMID 34680349, 2021). "The previous studies reported that HMGA2 could contribute to breast cancer cell metastasis, while inhibit apoptosis." (PMID 34281530, 2021). "Our data showed that circFBXL5 could promote the 5-FU resistance of breast cancer by regulating miR-216b/HMGA2 axis." (PMID 34281530, 2021). "For example, HMGA2 induces the proliferation of cancer cells (ovarian cancer, leukemia, breast cancer, and colorectal cancer) promoting cell-cycle entry and inhibiting apoptosis, but it can also exhibit effects on pathways involved in DNA repair and epithelial-to-mesenchymal transition." (PMID 34439740, 2021). "However, our recent report on HMGA2 in breast cancer clearly revealed a prognostic significance of cytoplasmic HMGA2." (PMID 34302528, 2021). "In addition, HMGA2 was a target of miR-216b, and its overexpression also reversed the regulation of miR-216b overexpression on the 5-FU resistance of breast cancer." (PMID 34281530, 2021). "It was shown that HMGA2 silencing promotes apoptosis by reducing antiapoptotic Bcl-2 expression in ovarian cancer and we found that HMGA2 derepresses the expression of Bcl-2 by inhibiting miR-34a in breast cancer, thereby promoting the Bcl-2 antiapoptotic pathway." (PMID 33668453, 2021). "In breast cancer, downregulated miR-143 is related with the poor prognosis of the patients with breast cancer, and miR-143 can effectively inhibit the malignant behaviors of the breast cancer cells via targeting HMGA2." (PMID 34416888, 2021). "In conclusion, our data showed that circFBXL5 might promote the 5-FU resistance of breast cancer by regulating cell migration, invasion and apoptosis, possibly by regulating the miR-216b/HMGA2 axis." (PMID 34281530, 2021). "Moreover, the loss of let-7 levels in breast carcinoma initiates and maintains the oncostatin O (OSM)-induced EMT genetic program, and HMGA2 acts as a master switch in this event." (PMID 34722255, 2021). "In addition, Let-7 has been reported to play crucial roles in metastasis by targeting HMGA2 in nasopharyngeal carcinoma, in breast cancer and in oral cancer." (PMID 34722255, 2021). "Metformin resists the growth of breast cancer through targeting Sp1/HMGA2 signal." (PMID 32031335, 2020). "Indeed, HMGA2 expression increased proportionally with anchorage-independent growth and metastasis of many epithelial tumors including colon, gastric, and breast cancer cells." (PMID 32365712, 2020). "Taking a step further, we then attempted to clarify how metformin regulates HMGA2 in breast cancer." (PMID 32031335, 2020). "In addition, ectopic HMGA2 expression also remodels chromatin in mammary tumor and breast cancer to a closed conformation at the Cdh1 locus by hypermethylation governed by HMGA2 interaction with DNA methyltransferases (DNMT3A)." (PMID 32365712, 2020). "As a novel target, HMGA2 is obviously decreased in metformin‐resisted breast cancer." (PMID 32031335, 2020). "For instance, HOTAIR is a miR-148a sponge that regulates Slug to promote EMT expression in esophageal cancer, lincRNA-ROR induces EMT through ZEB regulation by inhibition of miR-205 in breast cancer and H19 operates as a sponge for let-7 to increase HMGA-2 mediated EMT in pancreatic cancer." (PMID 32575745, 2020). "In summary, we concluded that metformin could control HMGA2 transcription through targeting Sp1 in breast cancer." (PMID 32031335, 2020). "We then analyzed whether metformin could regulate the promoter activities of HMGA2 in breast cancer cells." (PMID 32031335, 2020).
breast cancer (continued). "Moreover, it was recently reported that HOTAIR influences cell metastasis and apoptosis through miR-20a-5p/HMGA2 signaling in breast cancer." (PMID 31481088, 2019). "This newly discovered function of HMGA2 in promoting protein PARylation was confirmed in MDA‐MB‐231 overexpressing HMGA2 which showed a significant increase in PARylated proteins when compared to mock controls and in MDA‐MB‐436 breast cancer cells following siRNA‐mediated silencing of HMGA2." (PMID 30289618, 2019). "Moreover, RKIP extends its indirect regulatory role downstream of HMGA2, in a number of additional let-7/HMGA2 targets involved in the metastatic process, as shown by gene and microRNA expression analyses performed in breast cancer cell lines." (PMID 30149591, 2018). "HMGA2 overexpression has been frequently detected in several malignant neoplasms and inhibition of its expression shown to prevent tumor transformation in several cancer types, including thyroid cell, tongue squamous cell carcinoma and breast cancer." (PMID 30474570, 2018). "Data have collectively indicated that the high level of HMGA2 could serve as a novel biomarker to evaluate the prognosis of patients with various cancers such as breast cancer, lung cancer, ovarian cancer, colorectal cancer, and gastric cancer." (PMID 29997523, 2018). "Furthermore, HMGA2 depletion in breast cancer cells resulted in downregulation of miR-29 and induction of its target TET1, which in turn demethylates the promoter of the metastasis-suppressor HOXA9 and promotes its transcription." (PMID 30149591, 2018). "Furthermore, our results provide a mechanistic rationale for the use of a PAR1 inhibitor for breast cancer therapy and the employment of Akt and HMGA2 as potential biomarkers for efficacy." (PMID 30065181, 2018). "When HMGA2 was depleted by siRNA in breast cancer cells, an up-regulation of TET1 was noted." (PMID 28587163, 2017). "The idea that TET1 is itself epigenetically regulated and that its activation regulates a network of genes has been supported in a breast cancer cell line by experiments manipulating expression of HMGA2 (high mobility group at-hook 2), which is an upstream repressor of TET1 expression." (PMID 28587163, 2017). "Thus, by altering the phosphorylation status of STAT3, Dov targets the STAT3/LIN28/Let‐7/HMGA2 axis, which is emerging as an important oncogenic pathway for HMGA2 regulation in a subset of GB and breast cancer cells." (PMID 28500786, 2017). "It is previously known that HMGA2 chromosomal rearrangements are implicated in benign tumours of mesenchymal origin and overexpression of the HMGA2 protein is found in a variety of malignant tumour types such as breast cancer, pancreatic cancer, oral squamous cell carcinomas as well as NSCLC." (PMID 26858029, 2016). "HMGA2 can promote breast cancer cell invasion by remodeling the extracellular matrix (ECM)." (PMID 26968810, 2016). "HMGA2 expression correlates with metastases and reduced survival, and is increased in several malignancies, such as lung, prostate, colon, pancreatic, gastric and breast cancer." (PMID 27677077, 2016). "The inverse relationship between the expression levels of let-7 and HMGA2 was further supported by recent studies demonstrating that ectopic let-7 expression can inhibit cell growth and mammosphere formation by down-regulating RAS and HMGA2 in mouse breast cancers." (PMID 26399619, 2016). "Interesting results were obtained by analyzing HMGA2 expression in breast tumors coming from different geographical areas: 14 samples of breast cancers from African-American patients, 31 samples from Caucasian-American patients, and 14 samples from German patients." (PMID 25859543, 2015). "Recent studies have shown several members of let-7 family were diminished expression in breast cancer compared with normal breast tissues, and inhibited the breast cancer cell migration and invasive ability through regulating HMGA2, Lin28, GAB2, FN1, MAPK and MMPs." (PMID 25884389, 2015).
breast cancer (continued). "HMGA2 can enhance breast cancer metastasis by upregulating the pro-metastatic gene CXCR431." (PMID 25919570, 2015). "Interestingly, downregulation of let-7 initiated and maintained oncostatin M-induced EMT phenotypes in breast cancer, and that high mobility group A2 (HMGA2) acted as a switching actor in this progress." (PMID 25884389, 2015). "Let-7 has been reported to play a tumor suppressor role in lung and breast cancer by repressing oncogenes such as Hmga2 and Ras, which suggests that disruption of Let-7 processing by activation of Lin28 could promote the oncogenic phenotype." (PMID 22808086, 2012). "Breast cancer stem cells are also devoid of let-7, but abundantly express HMGA2 and ras36." (PMID 20179807, 2010). "However, the significantly higher gene expression in the relapse group of our study suggests that HMGA2 could serve as a biomarker for monitoring breast cancer relapse." (PMID 40686703, 2025). "Notably, HOTAIR could serve as a molecular sponge for miR-20a-5p, promoting breast cancer progression and tumorigenesis by activating the expression of the HMGA2 protein." (PMID 38561760, 2024). "Hence, we hypothesized that circFBXL5 might sponge miR-216b to regulate HMGA2, thereby participating in the regulation of 5-FU resistance in breast cancer." (PMID 34281530, 2021). "Interestingly, HMGA2 is re-expressed and becomes again highly elevated in benign as well as malignant neoplasms such as ovarian cancer, breast cancer, lung cancer, gastrointestinal cancer, and pancreatic cancer." (PMID 34302528, 2021). "In addition, increasing evidences had suggested that HMGA2 could facilitate 5-FU resistance in many cancers, like hepatoma cancer, colorectal cancer and breast cancer." (PMID 34281530, 2021). "Moreover, HOTAIR functions as a ceRNA for miR-20a-5p and upregulates a miR-20a-5p target, the high mobility group AT-hook 2 (HMGA2) gene, which enhances the proliferation, survival, migration, and invasion of breast cancer cells, and the growth of breast tumors." (PMID 32486413, 2020). "Finally, our data revealed that HMGA2 was involved in metformin‐suppressed breast cancer." (PMID 32031335, 2020). "Collectively, we concluded that metformin could alleviate breast cancer through targeting HMGA2." (PMID 32031335, 2020). "Here, we focus on whether HMGA2 takes part in metformin‐depressed breast cancer." (PMID 32031335, 2020). "Indeed, downstream of SMAD proteins, HMGA2 was resolved to directly activate zinc-finger transcription families Snail, Slug, and Twist and downregulate Inhibitor of differentiation 2 (Id2) in mammary tumor cells which altogether are known to repress E-cadherin (CDH1) expression." (PMID 32365712, 2020). "Considering the TCGA datasets and our meta-analysis, we identified correlation between high HMGA2 expression and head and neck cancer, pancreatic ductal adenocarcinoma, ccRCC, hepatocellular carcinoma, esophageal adenocarcinoma and ovarian carcinoma, except breast cancer and gastric cancer." (PMID 29997523, 2018). "Similarly, in human breast cancers, tumor suppressor miRNA let-7 which inhibits self-renewal capacity and promotes differentiation by repressing H-Ras and high mobility group AT-hook 2 (HMGA2)was found to be downregulated in the CD44+/CD24−/low BCSCs." (PMID 24977105, 2012). "In the literature, both HMGA2 and HOTAIR have been revealed to be effective in breast cancer development, progression, and metastasis." (PMID 40686703, 2025). "Evidence showed that interference of HMGA2 retarded migration, invasion and metastasis by repressing the Hippo-YAP signaling pathway in breast cancer." (PMID 38289488, 2024).